THEM5 (thioesterase superfamily member 5)
Description:
Has acyl-CoA thioesterase activity towards long-chain (C16 and C18) fatty acyl-CoA substrates, with a preference for linoleoyl-CoA and other unsaturated long-chain fatty acid-CoA esters. Plays an important role in mitochondrial fatty acid metabolism, and in remodeling of the mitochondrial lipid cardiolipin. Required for normal mitochondrial function.
Synonyms: ACOT15; FLJ37964
Tractability: No criterion of Open Targets' tractability assessment is met for any kind of drug.
Gene: Protein-coding gene on chromosome 1 (151,847,101 to 151,853,712, reverse strand). Ensembl gene ENSG00000196407.
Subcellular location: Mitochondrion matrix
Pathways (Reactome):
Metabolism: Mitochondrial Fatty Acid Beta-Oxidation
Gene Ontology:
Molecular function: long-chain fatty acyl-CoA hydrolase activity; protein binding
Biological process: long-chain fatty-acyl-CoA metabolic process; lipid metabolic process
Cellular component: mitochondrial matrix; mitochondrion
Genetic constraint (gnomAD): Loss-of-function variants: 29 observed, 26.5 expected, observed/expected ratio (o/e) 1.09, 90% interval 0.81 to 1.49. The upper end of that interval is the gene's LOEUF score, 1.49, which puts it in group 6 of 6, group 1 being the genes least tolerant of losing a copy. Missense variants: 235 observed, 280.8 expected, observed/expected ratio (o/e) 0.84, 90% interval 0.75 to 0.93. Synonymous variants: 81 observed, 108.19 expected, observed/expected ratio (o/e) 0.75, 90% interval 0.62 to 0.9.
Homologues: Orthologues: chimpanzee THEM5 (98% identical), macaque THEM4 (91% identical), dog THEM5 (83% identical), rabbit THEM5 (79% identical), guinea pig THEM5 (78% identical), mouse Them5 (77% identical), rat Them5 (74% identical), pig THEM5 (73% identical). Paralogues in human: THEM4 (34% identical).
Diseases named in the same sentence as THEM5 in open-access papers:
THEM5 is named in the same sentence as 1 disease in open-access papers, as found by Europe PMC text mining. Sharing a sentence is not in itself a finding about the gene and the disease. The quoted sentences say what the papers report.
Obesity (1 paper, 2015). Accumulation of substantial excess body fat. "The loss of Acot7, Acot11/Them1, Acot13/Them2, and Acot15/Them5 result in phenotypes ranging from increased neurodegeneration to altered susceptibility to high-fat diet induced obesity, fatty liver, and insulin resistance through unknown mechanisms that unexpectedly altered whole body metabolism." (PMID 25760036, 2015).